HDAC6 (histone deacetylase 6)
Diseases named in the same sentence as HDAC6 in open-access papers (continued):
Sharing a sentence is not in itself a finding about the gene and the disease.
peripheral neuropathy (22 papers, 2016 to 2026). A disorder affecting the peripheral nervous system. "The accumulated evidence shows that HDAC6 inhibition is strongly associated with alleviating peripheral neuropathy and neuropathic pain, and mitochondrial dysfunction in vivo and in vitro models of peripheral neuropathy." (PMID 35740277, 2022). "HDAC6 has been implicated in peripheral neuropathy, neuropathic pain, in CMT, and in chemotherapy-induced peripheral neuropathy." (PMID 35328416, 2022). "Dysregulated HDAC6 activity leads to development of peripheral neuropathy and closely associated neuropathic pain by destabilizing microtubules and exacerbating nerve injuries." (PMID 34531721, 2021). "Here, we assessed the potential therapeutic effect of HDAC6 inhibitors on peripheral neuropathy with HSPB1 mutation using in vitro model of motor neurons derived from induced pluripotent stem cells (iPSCs) of CMT2F and dHMN2B patients." (PMID 28105056, 2016). "Accumulating evidence shows that HDAC6 inhibition is strongly associated with alleviating peripheral neuropathy and neuropathic pain, as well as mitochondrial dysfunction, in in vivo and in vitro models of peripheral neuropathy." (PMID 34531721, 2021). "In particular, increased HDAC6 activity is specifically detrimental to neurons, and its dysregulation is closely interlinked with the occurrence of peripheral neuropathy, neuronal microtubule instability, and reduced mitochondrial axonal transport." (PMID 37056668, 2023). "HDAC6 is a key regulator in mitochondrial dynamics and it is involved in mitochondrial dysregulation in peripheral neuropathies; thus, HDAC6 inhibitors are being investigated as potential therapies for multiple peripheral neuropathic disorders." (PMID 35625553, 2022). "Dysregulated HDAC6 correlates with peripheral neuropathy development, neuronal microtubule instability, and decreased axonal transport of mitochondria." (PMID 34531721, 2021). "Though a deep discussion of non-neuronal HDAC6 activity in mitochondrial function and dynamics is outside the scope of this review, these findings suggest multiple points of potential therapeutic intervention by HDAC6 inhibition in peripheral neuropathy." (PMID 34531721, 2021). "Here, we review emerging studies and integrate recent advances in understanding the unique connection between peripheral neuropathy and mitochondrial dysfunction through HDAC6-mediated interactions." (PMID 34531721, 2021). "In this review we summarized how HDAC6 activity is intertwined in development of peripheral neuropathy through dysfunctional mitochondrial axonal transport and sensory nerve damage." (PMID 34531721, 2021). "In a cisplatin-induced peripheral neuropathy model, the HDAC6 inhibitor ACY-1083 prevented development of mechanical allodynia and completely attenuated established mechanical allodynia, spontaneous pain, and numbness." (PMID 31024248, 2019). "Our results suggest that the neurons derived from patient-specific iPSCs can be used in drug screening including HDAC6 inhibitors targeting peripheral neuropathy." (PMID 28105056, 2016). "Additionally, the ability of HDAC6 inhibitors to protect against chemotherapy-induced peripheral neuropathy further underscores their potential to improve patient quality of life irrespective of HDAC6-mediated anticancer activity." (PMID 39941046, 2025). "In a reverse-translational in vivo experiment, the authors showed that histone deacetylase 6 (HDAC6) inhibition could alleviate the drug-induced peripheral neuropathy." (PMID 38067315, 2023). "The mechanisms that lead to mitochondrial dysfunction in peripheral neuropathy are poorly understood, however, the Class IIb histone deacetylase (HDAC6), may play an important role in the process." (PMID 34531721, 2021). "HDAC6 is a key regulator in multiple mechanisms of mitochondrial dynamics and may contribute to mitochondrial dysregulation in peripheral neuropathy." (PMID 34531721, 2021).
peripheral neuropathy (continued). "Taken together, HDAC6 activity in both mitochondrial function, mitochondrial transport, and microtubule stability connect multiple lines of investigation to the mechanistic underpinnings of peripheral neuropathy." (PMID 34531721, 2021). "In this review, we discuss the emerging topic of HDAC6 activity and non-histone protein modifications linked to development of peripheral neuropathy by altered mitochondrial function and transport." (PMID 34531721, 2021). "Therefore, one of the strongest points of this study is that CMT2F- and dHMN2B-specific in vitro cellular models can be applied for the screening of putative therapeutic molecules, such as HDAC6 inhibitors on peripheral neuropathy." (PMID 28105056, 2016). "Therefore, therapies targeting HDAC6 may restore balanced mitochondrial activity, mediate potential repair of peripheral neuropathy, and alleviate neuropathic pain." (PMID 34531721, 2021). "Further investigation and deep understanding of HDAC6 mediated interactions in microtuble stabilization and mitochondrial transport may lead to clinical use of targeted HDAC6 inhibition therapies, which are sorely needed for treatment of peripheral neuropathy and neuropathic pain." (PMID 34531721, 2021). "Thus, investigating the effect of HDAC6 inhibition in other peripheral neuropathies could be another interesting route for further investigations." (PMID 27957719, 2017). "Recent work has shown that HDAC6 inhibitors, such as Ricolinostat, an inhibitor of histone deacetylase 6, have been effective in improving DPN, chemotherapy-induced peripheral neuropathy (CIPN),and peroneal muscular dystrophy (CMT) type 2 disease in animal models with good safety and tolerability." (PMID 37056668, 2023). "In terms of MOF, there is little data suggesting that MOF is dysregulated in peripheral neuropathy nor does HDAC6 interact with MOF, but it is known to be involved in mtDNA regulation." (PMID 34531721, 2021). "In the model of cisplatin-induced cognitive dysfunction, we showed that treatment with a different HDAC6 inhibitor (ACY-1215) that is not brain penetrant was sufficient to reverse cisplatin-induced peripheral neuropathy but not cisplatin-induced cognitive dysfunction." (PMID 34976203, 2022).
neurological diseases (13 papers, 2019 to 2024). "Acetylation of α-tubulin K40, a well-known substrate of HDAC6, is implicated in neuroprotection after HDAC6 inhibition in many neurological diseases." (PMID 35585040, 2022). "HDAC6 is reported to interact with microtubule-associated protein tau and is likely to be responsible for acetylation–phosphorylation switch of tau to affect neurological diseases progression." (PMID 31652644, 2019). "The HDAC6 protein participates in multiple biological processes of which several have implications in neurological disorders." (PMID 38918466, 2024). "On the other hand, high‐selective inhibitors or small interfering RNAs targeting HDAC6 exhibited neuroprotective effects in some neurological disease models." (PMID 37665135, 2024). "In light of these contradictory findings, further investigation is required to fully understand the role of HDAC6 in neurological disorders." (PMID 38918466, 2024). "Histone deacetylase 6 (HDAC6) has been implicated in various diseases, including neurological diseases, heart diseases and inflammatory diseases." (PMID 38632516, 2024). "In the present study, we therefore aimed at collecting HDAC6 protein targets that are experimentally validated and reported in CNS or have an impact on neurological disorders." (PMID 38918466, 2024). "In summary, our study shows that HDAC6 is one of the main hub proteins in the molecular interaction networks of several neurological diseases." (PMID 38918466, 2024). "For decades, high selective inhibitors or small interfering RNAs targeting HDAC6 exhibited neuroprotection in several experimental models of neurological disorders." (PMID 37138816, 2023). "However, in the context of neurological disorders, HDAC6 is reported to have seemingly contradictory effects." (PMID 38918466, 2024). "In addition, the exact neuroprotective effect offered by HDAC6 or SIRT2 inhibitors in neurological diseases is still unclear." (PMID 37150812, 2023). "HDAC6 plays a key role in tumors, neurological diseases, and inflammatory diseases." (PMID 35652048, 2022). "Acetylation of these proteins regulated by HDAC6 may modulate protein functions and contribute to neurological disorders." (PMID 35585040, 2022). "A growing body of evidence indicates that HDAC6 inhibition is a promising target for neurological diseases; however, the mechanism by which HDAC6 is involved in these neurological disorders remains unknown." (PMID 35585040, 2022). "Inhibition of HDAC6 suppresses neuritic tau bead formation in vivo, suggesting targeting on HDAC6 may bring some benefits to stop the onset of neurological disorders." (PMID 31652644, 2019). "In conclusion, the HDAC6 network created in the present study is a novel and valuable resource for the understanding of the HDAC6 regulatory mechanisms, thereby providing a framework for the integration and interpretation of omics data from neurological disorders and pharmacodynamic assessments." (PMID 38918466, 2024). "Therefore, the identification of novel HDAC6 substrates may contribute to understanding how HDAC6 participates in the development of neurological diseases." (PMID 35585040, 2022). "Recent studies show that histone deacetylase 6 (HDAC6) has important roles in the human brain, especially in the context of a number of nervous system disorders." (PMID 30935091, 2019).
hematologic malignancies (8 papers, 2018 to 2025). "Here we discuss the therapeutic effects of HDAC6 inhibitors in B cell-associated hematological malignancies, such as MM and B-NHL, which are resistant to many targeted therapies." (PMID 32676030, 2020). "While this article discusses the role of HDAC6 in B cell-associated hematological malignancies, there are few reports of HDAC6 participating in the development or function of normal B cells." (PMID 32676030, 2020). "Several studies have shown that abnormal expression or activity of HDAC6 is associated with a variety of diseases, including B cell-associated hematological malignancies." (PMID 32676030, 2020). "Here we discuss the clinical therapeutic development of HDAC6 inhibitors against B cell-associated hematological malignancies, including those resistant to targeted therapies, and summarized HDAC6 inhibitors used in preclinical or clinical investigations." (PMID 32676030, 2020). "HDAC6 inhibitors used in B cell-associated hematological malignancies." (PMID 32676030, 2020). "Among them, HDAC6, which is an enzyme that deacetylates α-tubulin, is increasingly recognized as a potential therapeutic target in hematologic malignancies." (PMID 41249257, 2025). "Some of the single inhibitors selective for HDAC6 are in clinical trials for the treatment of solid and hematologic malignancies, whereas the five pan-HDAC inhibitors are approved for clinical use." (PMID 38004560, 2023). "ACY-1215 is classified as a selective HDAC6 inhibitor and also show potent anticancer activity mainly in hematologic malignancies." (PMID 31652644, 2019). "The potential of selective inhibition of HDAC6 has been widely discussed for the treatment of hematologic malignancies." (PMID 31652644, 2019). "Another possible role of HDACs in the development of hematological malignancies is related to the functional network of HDAC6 and HSP90." (PMID 30096875, 2018). "Various studies of HDAC6 inhibitors alone and in combination with other agents provide strong scientific rationale for the evaluation of these new agents in the clinical setting of hematological malignancies." (PMID 30096875, 2018).
kidney diseases (8 papers, 2018 to 2023). "Deranged HDAC6 activity has also been implicated in various disorders, such as cancer, neurodegenerative diseases, and kidney diseases." (PMID 36552715, 2022). "There were pieces of evidence showing that abnormal B-cell differentiation was associated with a less severe form of kidney disease, which could be corrected by selective HDAC6 inhibition." (PMID 37545520, 2023). "HDAC6 expression and activity have recently been shown to be increased in kidney disease in a number of studies." (PMID 37545520, 2023). "A substantial amount of validated studies has identified HDAC6 as a pivotal modulator of inflammation and a promising therapeutic candidate for the management of a variety of renal diseases." (PMID 37545520, 2023). "HDAC6 has been identified as a driver of ciliary disassembly, and its activation is required in the context of various signaling events related to kidney disease and is also involved in tracheal ciliary dysfunction in response to cigarette smoke." (PMID 36290484, 2022). "It has been demonstrated that histone deacetylase 6 (HDAC6) is involved in various kidney diseases in experimental study." (PMID 33896334, 2021). "There are an increasing number of evidences indicating that the expression and activity of HDAC6 are increased in many kidney diseases." (PMID 33896334, 2021). "Here, we discuss the unique function of HDAC6 and recapitulate the alluring potential of its inhibitors in kidney diseases." (PMID 30134806, 2018). "Growing evidence has demonstrated that the expression and activity of HDAC6 are increased in various kidney diseases, and inhibiting HDAC6 has mitigated the progression of kidney injury." (PMID 30134806, 2018). "Herein, we pay special attention to the role of HDAC6 in the progression of kidney diseases and the tantalizing promise of its inhibitor, which could facilitate the advancement of HDAC6-targeted therapeutic methods for complications of RT." (PMID 37545520, 2023). "HDAC6, the class IIb deacetylase, has recently emerged as a critical cytokine in kidney diseases." (PMID 33896334, 2021). "Aberrant expression of HDAC6 is involved in several physiological processes such as stress response (ER stress), apoptosis and autophagy that play crucial roles in tumors, neurodegenerative disorders, inflammation and kidney diseases." (PMID 31894849, 2020). "HDAC6 has recently emerged as a vital cytokine in kidney diseases." (PMID 30134806, 2018). "In fact, HDAC6 inhibitors effectively limit the progression of kidney diseases, suggesting that targeting HDAC6 may provide a novel treatment approach." (PMID 30134806, 2018). "HDAC6 plays a aggravating role in kidney diseases, and up-regulation of HDAC6 could exacerbate kidney diseases." (PMID 30134806, 2018). "In this review, we focus on the role of HDAC6 in the pathology of kidney diseases and recapitulate the alluring potential of its inhibitors, which may aid in the development of HDAC6-targeted therapies for kidney diseases." (PMID 30134806, 2018). "Furthermore, HDAC6 is closely related to other kidney diseases, including LN and AKI." (PMID 30134806, 2018). "Furthermore, HDAC6 inhibitors have shown powerful potential therapeutic effects in multiple diseases, such as cancer, neurodegenerative diseases, cardiovascular diseases, and kidney disease, among others." (PMID 30134806, 2018).
cardiovascular diseases (4 papers, 2017 to 2024). "Histone deacetylase 6 (HDAC6) belongs to a class of epigenetic targets that have been found to be a key protein in the association between tumors and cardiovascular disease." (PMID 38947757, 2024). "Here, we review the association between HDAC6 and cardiovascular disease, the research progress of HDAC6 inhibitors in the treatment of cardiovascular disease, and discuss the feasibility of combining HDAC6 inhibitors with other therapeutic agents to treat cardiovascular disease." (PMID 38947757, 2024). "Despite the fact that histone deacetylase (HDAC) inhibitors have been tested to treat various cardiovascular diseases, the effects of selective HDAC6 inhibitor ACY1215 on infarct size during cardiac ischemia-reperfusion (IR) injury still remain unknown." (PMID 32178737, 2020).
bacterial infection (3 papers, 2017 to 2024). "This study fosters future in-depth investigation to allow the complete elucidation of the molecular mechanisms underlying HDAC6’s role in bacterial infections." (PMID 38371939, 2024). "Knocking out Hdac6 expression from CF mice improves growth, reverses depression-like behavior, and normalizes inflammatory responses to bacterial infection." (PMID 36062879, 2022). "Our genetic approach unequivocally assigns a specific role to HDAC6 in innate cells during bacterial infection." (PMID 29281743, 2017). "A very important milestone for the elucidation of the consequence of HDAC6 activity in bacterial infections is herein described, unveiling for the first time the role of a potent HDAC6 inhibitor in interfering with biofilm formation and modulating virulence factors of P. aeruginosa." (PMID 38371939, 2024). "However, whether HDAC6 regulates innate immunity during bacterial infection remains unexplored." (PMID 29281743, 2017). "Our data show that Hdac6-/- bone marrow-derived dendritic cells (BMDCs) have a higher bacterial load than Hdac6+/+ cells, correlating with weaker induction of IFN-related genes, pro-inflammatory cytokines and nitrite production after bacterial infection." (PMID 29281743, 2017). "The role of HDAC6 in the adaptive CD4 + T-cell response has been studied in several autoimmune and inflammatory situations such as colitis and cardiac allograft rejection; however, little is known about its role in innate immunity and bacterial diseases." (PMID 29281743, 2017).
hematologic cancers (3 papers, 2022 to 2025). "Two selective HDAC6 inhibitors, ACY-1215 (Ricolinostat), and ACY-241 (Citarinostat) are currently being studied in clinical trials for hematologic and non-hematologic cancers." (PMID 35328416, 2022). "In particular, given the association of HDAC1 and HDAC6 with the progression of AML and CLL – two hematologic cancers for which venetoclax has already received FDA approval – we elected to focus on achieving HDAC1 and HDAC6 selectivity in our dual BCL‐2/HDAC inhibitors." (PMID 40370107, 2025).
metabolic disorders (3 papers, 2015 to 2024). "Future studies could investigate the potential metabolic effects of HDAC6 inhibition in animal models of metabolic disorders, as well as the mechanisms underlying these effects." (PMID 38409164, 2024). "This suggests that HDAC6 inhibition may have metabolic effects beyond the cardiovascular system, which could be relevant for the treatment of metabolic disorders." (PMID 38409164, 2024).
adenocarcinoma (2 papers, 2016 to 2021). A common cancer characterized by the presence of malignant glandular cells. "HDAC6 overexpression in adenocarcinoma cells promotes proliferation through its deacetylase activity." (PMID 27499032, 2016).
central nervous system diseases (2 papers, 2024). "Accumulating evidences show that HDAC6‐targeted treatment is a considerable therapeutic strategy in central nervous system diseases for its neuroprotective and regenerative effects." (PMID 37665135, 2024). "HDACi I and J are non-hydroxamate HDAC6 inhibitors designed to avoid the genotoxicity commonly associated with hydroxamates and are optimized for central nervous system disorders with enhanced brain accessibility." (PMID 39063958, 2024).
immune system disease (2 papers, 2020 to 2022). "Therefore, we further believe that abnormal HDAC6 gene expression caused by an abnormal HDAC6 methylation level may be one of the pathological causes of immune system disorders and emotional depression in QSBS-EMS patients." (PMID 35449808, 2022).
inflammation (2 papers, 2018 to 2021). Aberrant reaction of the microcirculation characterized by movement of fluid and leukocytes from the blood into extravascular tissues. "It is striking that HDAC6 inhibition suppressed bone and cartilage damage more than synovial inflammation, emphasizing the inhibitory effect of HDAC6 on activated FLS during synovial inflammation." (PMID 34225810, 2021).